MIR3180-5 (microRNA 3180-5)
Synonyms: hsa-mir-3180-5; mir-3180-5
Gene: MicroRNA gene on chromosome 16 (2,135,977 to 2,136,129, reverse strand). Ensembl gene ENSG00000264397.
Gene Ontology:
Biological process: miRNA-mediated post-transcriptional gene silencing